ACE (angiotensin I converting enzyme)
Diseases named in the same sentence as ACE in open-access papers (continued):
Sharing a sentence is not in itself a finding about the gene and the disease.
sarcoidosis (continued). "Both serum NSE and sIL-2R levels, but not serum ACE levels, were significantly higher in sarcoidosis patients who had been treated with OCS than in those who had never received OCS therapies." (PMID 35663496, 2022). "The prominent negative predictive value of triple-negative NSE, ACE, and sIL-2R also suggests that the combination of these markers is useful for excluding sarcoidosis during diagnosis." (PMID 35663496, 2022). "The inclusion of NSE in combination with ACE and sIL-2R improved the sensitivity and negative predictive value for the diagnosis of sarcoidosis compared with each marker alone." (PMID 35663496, 2022). "In our study, the sensitivity of NSE alone seems comparable to those of the traditional markers ACE and lysozyme, but its combinations with ACE and sIL-2R resulted in a greater sensitivity, providing the additional value of NSE in combination with such traditional markers for sarcoidosis." (PMID 35663496, 2022). "Compared to alveolar macrophages from non-smokers, the ACE activities in those from smokers and patients with sarcoidosis are, respectively, three and five times greater (p < 0.01)." (PMID 36291609, 2022). "Pulmonary function test and angiotensin-converting enzyme (ACE) blood levels were also ordered to rule out sarcoidosis and both of them were normal." (PMID 34465352, 2021). "However, in sarcoidosis patients both serum and BALF levels of KL-6 correlate with higher serum ACE levels and CD4+/CD8+ ratio." (PMID 32760396, 2020). "We observed a significant direct correlation between urinary calcium and chitotriosidase activity in patients with sarcoidosis (r = 0.2564, p = 0.009), but not with ACE (r = 0.0938, p = 0.1535)." (PMID 33195314, 2020). "To evaluate the patient for infiltrative disease, i.e., lymphoma, sarcoidosis, and tuberculosis, we tested serum lactate dehydrogenase (LDH) and angiotensin-converting enzyme (ACE) levels, which were reported in the normal range (LDH: 353 (230–460 U/L) and ACE: 51.1(8–52 U/L))." (PMID 33143716, 2020). "An elevated CRP of 70 (< 10 mg/L) and a normal ACE level of 93 (30–115 U/l) was interpreted as no sign of sarcoidosis reactivation." (PMID 31771516, 2019). "Serum sIL-2R is a sensitive biomarker and superior to ACE in establishing the diagnosis of sarcoidosis and can be used to rule out sarcoidosis in patients suspected of sarcoidosis." (PMID 31622413, 2019). "The role of ACE levels in diagnosing or managing sarcoidosis is controversial, as ACE level is not a sensitive enough test for the diagnosis of systemic sarcoidosis." (PMID 31737633, 2019). "Cerebral spinal fluid (CSF) ACE level is not reliable enough in coming to the diagnosis in an isolated neuro-sarcoidosis without systemic involvement." (PMID 29983918, 2018). "Sarcoidosis patients in the active phase of the disease were significantly higher YKL-40, sIL-2R, hs-CRP levels and ACE activity than those in the inactive phase, while ADA activities and neopterin levels did not display any significant difference between the active and inactive disease groups." (PMID 30154391, 2018). "Sarcoidosis patients in the active phase of the disease were significantly higher YKL-40, sIL-2R, ACE and hs-CRP levels than those in the inactive phase, while ADA activities and neopterin levels did not display any significant difference between the active and inactive disease groups." (PMID 30154391, 2018). "The results indicate that serum YKL-40, sIL-2R, ACE and hs-CRP concentrations may be useful marker for monitoring sarcoidosis disease activity." (PMID 30154391, 2018). "While there are several studies demonstrating that serum ACE levels are elevated in active sarcoidosis, the serum ACE levels were not significantly different between active and inactive sarcoidosis." (PMID 30154391, 2018). "In conclusion, our results indicate that serum YKL-40, sIL-2R, ACE and hs-CRP concentrations may be useful panel marker for monitoring sarcoidosis disease activity." (PMID 30154391, 2018).
sarcoidosis (continued). "Further studies are needed to investigate the clinical significance of ACE level in sarcoidosis with and without ocular involvement." (PMID 29785303, 2018). "There were no signs of generalized sarcoidosis because the patient had a normal serum ACE level with a normal chest radiograph and showed no uveitis." (PMID 29197349, 2017). "Rise of serum ACE activity has been found in 93 % of patients with active sarcoidosis, 41 % of patients with TB and 56 % of patients with nonspecific inflammatory lung diseases including fibrosing alveolitis, histiocytosis X, and pneumoconiosis." (PMID 26879979, 2016). "There are two patients in the ocular sarcoidosis group, and one patient in the no sarcoidosis group taking an ACE inhibitor." (PMID 26799486, 2016). "In the chest CT scan, no pulmonary or mediastinal evidence of sarcoidosis was noted; additionally, the serum concentrations of angiotensin-converting enzyme (ACE) and soluble IL2 receptor (sIL2R) were normal." (PMID 27623618, 2016). "In a case report, a 32-year-old Japanese woman with Turner's syndrome was found to have elevated LFTs and serum ACE levels and was found to have sarcoidosis based on the noncaseating granulomas on lymph node biopsy." (PMID 25705228, 2015). "In healthy individuals, the circulating ACE level is very stable, as opposed to higher concentrations of circulating ACE in patients with granulomatous diseases (sarcoidosis in particular) and Gaucher’s disease." (PMID 23560051, 2013). "In our case, diagnosis of sarcoidosis was done based on skin lesions, high serum ACE, and calcium levels and typical noncaseating granulomas determined in the skin biopsy." (PMID 24381778, 2013). "Although not statistically significant, BAL lymphocytosis, particularly with a high CD4/CD8 ratio, and an elevated serum ACE, were highly suggestive of sarcoidosis in the context of nonspecific cutaneous involvement with no other systemic findings." (PMID 23521826, 2013). "Serum Angiotensin Converting Enzyme (ACE) levels measured in sarcoidosis to monitor disease progression (which are the only serum biomarker in routine clinical use) are non-specific as ACE is elevated in a number of diseases including tuberculosis itself." (PMID 22815689, 2012). "CSF abnormalities are seen in 80% of patients with neurosarcoidosis, but are non-specific; likewise, serum and CSF ACE (consistently normal in this patient) are also an insensitive test for sarcoidosis." (PMID 20157431, 2010). "In the present case, the absence of clinical signs of the disease in other organs, a normal chest x ray, a normal ACE level and histologic findings (intrahepatic cholestasis without granulomas) would exclude sarcoidosis." (PMID 22308126, 2010). "Normal serum calcium and ACE levels, along with histopathology suggestive of diffuse granuloma annulare, and a negative reticulin stain ruled out sarcoidosis." (PMID 20418988, 2010). "Serum ACE is elevated in approximately 60% of patients with sarcoidosis, but levels do not correlate with stage or prognosis." (PMID 17355633, 2007). "In contrast, sarcoidosis is defined by non-caseating granulomas, lacks specific autoantibodies, and serum ACE may be elevated but lacks sensitivity." (PMID 41226948, 2025). "ACE levels are a non-specific marker of sarcoidosis, and as described in the clinical case, ACE values ​​may be normal despite the diagnosis of sarcoidosis, but they can be elevated in up to 60% of patients." (PMID 39867510, 2025). "Angiotensin converting enzyme (ACE) test was negative, and the patient did not have sarcoidosis." (PMID 39825368, 2025). "Angiotensin-converting enzyme (ACE) level was within normal limits, and sarcoidosis was ruled out." (PMID 41561301, 2025). "Sarcoidosis was excluded as serum calcium and ACE levels were normal." (PMID 41356974, 2025). "However, ACE levels have a poor sensitivity for detecting sarcoidosis, so this result did not exclude ICI-induced SLR from the differential diagnosis." (PMID 39872587, 2024).
sarcoidosis (continued). "Indeed, the positive predictive value of increased ACE levels for the diagnosis of sarcoidosis was 12.76%, while the negative predictive value (chance for a negative diagnosis of sarcoidosis in patients with normal ACE levels) was 94.6%." (PMID 39768579, 2024). "Angiotensin-converting enzyme (ACE) levels may be raised in sarcoidosis, but this increase is neither specific nor sensitive." (PMID 39110261, 2024). "We found that normal ACE levels had a high negative predictive value (94.6%), while elevated ACE levels demonstrated low positive predictive value, sensitivity, and specificity for diagnosing sarcoidosis." (PMID 39768579, 2024). "The serum ACE level increased in patients with sarcoidosis, dropped to normal with improvement in condition during treatment, and increased again after the recurrence of sarcoidosis." (PMID 37868968, 2023). "Even though the rise in ACE levels in a patient may increase suspicion of sarcoidosis, the absence of an elevated ACE level is insufficient to rule out the diagnosis." (PMID 37273881, 2023). "The ACE concentration did not depend on the activity of sarcoidosis." (PMID 37510860, 2023). "The possibility of elevated ACE levels in sarcoidosis was explained by the fact that granulomas of epithelioid cells may be primarily involved in ACE biosynthesis rather than phagocytosis and catabolism." (PMID 35615369, 2022). "Angiotensin converting enzyme (ACE) and soluble interleukin-2 receptor (sIL-2R) are the most widely used serum markers of sarcoidosis; they can easily be detected in the serum and bronchoalveolar lavage (BAL) fluid of sarcoidosis patients and have relative prognostic value." (PMID 30154391, 2018). "Elevated serum ACE level usually represents sarcoidosis with high negative predictive values, but the ACE level can also rise in several circumstances, such as Gaucher's disease, tuberculosis, leprosy, histoplasmosis, untreated hyperthyroidism, psoriasis, and lymphoma." (PMID 24716039, 2014). "Therefore, although an elevated serum ACE level is not a specific finding for sarcoidosis, serial measurements of serum ACE level are useful in the evaluation of treatment response." (PMID 24555559, 2014). "In addition, negative gallium scans with normal serum ACE levels appear to have a high predictive value for excluding active sarcoidosis." (PMID 19727352, 2007). "Therefore, low or normal ACE levels, as observed in this patient, do not exclude sarcoidosis." (PMID 40709165, 2025). "It seems that ACE may not be an accurate indicator of sarcoidosis activity." (PMID 37510860, 2023). "The serum ACE level gradually decreased to normal in about 12 months of melatonin treatment, and in about 24 months, the skin lesions completely disappeared and the pulmonary function returned to normal; no recurrence of sarcoidosis was observed during the treatment." (PMID 37868968, 2023). "Thus, if an individual is below average in sACE level, even though sarcoidosis increases a person’s blood ACE level, it may not be diagnosed with the disease on the basis of blood ACE activity." (PMID 36291609, 2022). "His chest X-ray was normal, T-SPOT.TB was negative, and serum angiotensin-converting enzyme (ACE) was undetectable, but eventually, a lymph node biopsy confirmed features of sarcoidosis." (PMID 39677126, 2024). "Concerning the comparison with existing clinical biomarkers for sarcoidosis, U-ATX showed a weak negative correlation to ACE, P-ATX a weak positive correlation to both ACE and sIL-2R, and PS-PLA1 a weak positive one to sIL-2R." (PMID 35288647, 2022). "His investigations revealed highly positive Mantoux test, negative QuantiFERON test, elevated serum ACE, and HRCT of chest showing features of sarcoidosis." (PMID 28534271, 2017). "Serum ACE is a nonspecific marker but in our case, we relied upon HRCT and took ACE as a supportive tool to diagnosis sarcoid." (PMID 28534271, 2017).
sarcoidosis (continued). "Of note, levels of non-specific markers of inflammation as well as “sarcoidosis-related” serum markers, such as sIL2R, ESR, CRP, and ACE level, did not correlate with pulmonary function measures or severity score." (PMID 24199653, 2013). "Sarcoidosis was also ruled out because chest radiography revealed no significant findings including BHL, although sIL2R was slightly elevated, ACE was within the normal limit in the lab data and histological examination of the erythematous lesions didn’t include non-caseating granuloma." (PMID 39280458, 2024). "Angiotensin-converting enzyme (ACE) levels, as well as serum and urine calcium, were within normal limits; however, CDI due to sarcoidosis and neurosarcoidosis could not be excluded." (PMID 37551214, 2023). "On the other hand, both serum ACE levels and BAL CD4 and CD8 cell numbers were not indicative of sarcoidosis, and the tuberculin test created a dilemma as to whether we should start glucocorticoids in our patient, since the acid-bacilli cultures were pending." (PMID 18605996, 2008). "Furthermore, the present study demonstrated that elevated serum levels of NSE, but not ACE or sIL-2R, were significantly correlated with OCS use in sarcoidosis patients, which is consistent with previous findings that elevated levels of NSE have been related to increased systemic inflammation." (PMID 35663496, 2022).
Stroke (305 papers, 2004 to 2026). Sudden impairment of blood flow to a part of the brain due to occlusion or rupture of an artery to the brain. "Blood pressure control reduces the risk of stroke, cardiovascular death, and even MALEs, especially for angiotensin-converting enzyme (ACE) inhibitors or angiotensin-receptor blockers (ARBs)." (PMID 40806931, 2025). "These include the methylenetetrahydrofolate reductase (MTHFR) and angiotensin I converting enzyme (ACE) genes, which have been reported to generally associate migraine with stroke." (PMID 40724883, 2025). "The deletion of the angiotensin-converting enzyme (ACE) gene is linked to a hypercoagulable state and vasoconstriction, which can lead to stroke." (PMID 39148704, 2024). "For circulatory diseases, ACE inhibitors and CCBs were associated with a lower risk of stroke, and a better functional outcome after ischemic stroke." (PMID 39567981, 2024). "Compared with the diuretic group, the ACE inhibitor group had a 19% increased risk of stroke mortality (AHR, 1.19 [95% CI, 1.03-1.37]) and an 11% increased risk of combined fatal and nonfatal hospitalized stroke (AHR, 1.11 [95% CI, 1.03-1.20])." (PMID 38048133, 2023). "ACE inhibitors increased the risk of stroke outcomes by 11% compared with diuretics, and this effect persisted well beyond the trial period." (PMID 38048133, 2023). "Long-term follow-up supports the main findings that the diuretic group had similar cardiovascular outcomes and the ACE inhibitor group had higher stroke mortality risk." (PMID 38048133, 2023). "For example, the absolute risk of stroke for Black people who were taking calcium channel blockers was 2.57% compared to 3.99% for those taking ACE inhibitors/ARBs." (PMID 34508156, 2022). "The meta-analysis compounds results for ACE inhibitors and ARBs making it hard to determine causation based on positive correlation between medication and stroke risk." (PMID 34508156, 2022). "A lesser known but still significant complication is angioedema secondary to tPA administration, which can develop in certain individuals with risk factors such as angiotensin converting enzyme (ACE) inhibitor use and location of the stroke." (PMID 34436994, 2021). "Specifically, changes in ACE (Angiotensin Converting Enzyme), Collagen Binding Protein, or MTHFr affect the risk of stroke." (PMID 34325669, 2021). "Authors found that the ACE inhibitors plus folic acid therapy, compared with ACE inhibitors alone, reduced stroke risk." (PMID 30781775, 2019). "The combination of ACE inhibitor plus ARB was associated with a reduced risk of stroke compared with placebo (OR 0.80; 95% CrI 0.62–0.98; moderate confidence)." (PMID 26954482, 2016). "Combinations of DR inhibitor with ACE inhibitor/ARB were potentially associated with an increased risk of stroke: DR inhibitor plus ARB compared with ACE inhibitor plus ARB (1.44; 95% CrI 1.00–2.13; low confidence)." (PMID 26954482, 2016). "In the PROGRESS trial, an angiotensin converting enzyme (ACE) inhibitor reduced the risk of cognitive decline by 19 % largely because of a reduced risk of recurrent stroke." (PMID 27543171, 2016). "Recent research has shown that the ACE is involved in the pathological process of stroke and various cardiovascular diseases, many of which are risk factors for stroke." (PMID 26730961, 2016). "On macrovascular scale, ACE polymorphisms have been found to be associated with cerebrovascular accident." (PMID 27240348, 2016). "The unadjusted HRs of risk of stroke for users of statins and ACE inhibitor were 1.32 (95% CI 1.17 to 1.49) and 2.02 (95% CI 1.85 to 2.21), respectively." (PMID 22363662, 2012). "The present meta-analysis, including 10 070 cases and 22 103 controls from 50 published studies, explored the association between the ACE I/D polymorphism and stroke risk." (PMID 23049705, 2012). "The inferiority of ACE-inhibitors to CCB regarding stroke-risk was significant and based on moderate quality evidence (RR 1.19; 95% CrI 1.03 to 1.38)." (PMID 22480336, 2012).